NRGN (neurogranin)
Diseases named in the same sentence as NRGN in open-access papers (continued):
Sharing a sentence is not in itself a finding about the gene and the disease.
dementia (24 papers, 2015 to 2026). Loss of intellectual abilities interfering with an individual's social and occupational functions. "Most importantly, the current evidence positions neurogranin within a broader pathophysiological context: mTBI is increasingly recognized as a risk factor for dementia and neurodegenerative diseases." (PMID 40981206, 2025). "Neurogranin, associated with PSDs, plays a vital role in synaptic plasticity and long-term potentiation to enhance memory and cognition, also known to be downregulated in dementia patients." (PMID 36518382, 2022). "Adults with HIV-associated dementia have been found to have decreased levels of neurogranin in the frontal cortex, which at least to some extent, may be mediated by the proinflammatory cytokines IL-1β and IL-8." (PMID 30649659, 2019). "For example, neurogranin (NRGN) is a widely studied postsynaptic protein, showing higher levels with worse memory performance in prodromal AD, although contradicting results have been found for memory associations in cognitively normal (CN) individuals and in AD dementia." (PMID 40033427, 2025). "Increased neurogranin concentrations have also been reported in frontotemporal dementia and Parkinson’s disease with dementia, supporting the view that it reflects a generalizable mechanism of synaptic injury rather than a disease-specific signal." (PMID 40981206, 2025). "Proteins such as neurogranin and SNAP-25 are elevated in the CSF of patients with AD and other dementias and have been linked to suicidality." (PMID 39290301, 2024). "Accordingly, new CSF biomarkers (e.g. neurofilament light chain and neurogranin) have been used to optimize dementia diagnoses." (PMID 34816970, 2022). "The aim was to investigate the relationship between NPS and CSF biomarkers for synaptic (neurogranin [Ng], growth-associated protein 43 [GAP-43]) and axonal (neurofilament light [NFL]) injury in patients with dementia." (PMID 33203439, 2020). "Data available so far indicate that neurogranin is highly specific for AD; in fact, neurogranin levels in other dementia patients are similar." (PMID 27621274, 2016). "Patients with dementia or MCI due to AD showed elevated levels of CSF neurogranin (p < 0.001 for AD-D and p < 0.05 for MCI-AD) and YKL-40 (p < 0.05 for AD-D and p = 0.15 for MCI-AD) compared to mildly cognitively impaired subjects not diagnosed with AD." (PMID 26698298, 2015). "Chromogranin-A and secretogranin-1 exhibit characteristically dynamic changes in CSF expression according to disease stage in a manner similar to that of neurogranin: increased levels during early stages (i.e., MCI) and reduced levels during advanced dementia." (PMID 32284537, 2020). "Here, high YKL-40 levels were observed only in the preclinical stage of sporadic AD, while neurogranin levels remained high in the MCI and dementia stages." (PMID 32568193, 2020). "Levels of neurogranin were reported to be increased in CSF in AD, even at the stage of MCI, and predicted progression from prodromal AD to dementia, as well as rate of progression of MRI change in AD." (PMID 26733934, 2015). "It is often observed that GAP‐43, SNAP‐25, β‐synuclein, and neurogranin are not changed in non‐AD dementias." (PMID 40522075, 2025). "Of the biomarker values that did not undergo correction, YKL40, GFAP, NfL, neurogranin, pTau, and tTau were all increased in patients with AD-dementia or MCI who were A+ compared with CU individuals and patients with MCI who were A−." (PMID 36709293, 2023). "In the AD patient population, all NDEV markers except P-S396-tau followed a common pattern of progressive increase with dementia severity that was significant for total tau, NRGN, and REST, but not for Aß42 and P-T181-tau." (PMID 36155516, 2022). "Moreover, reduced NDEV levels of NRGN and REST with respect to controls were observed at both preclinical and dementia AD stages as well." (PMID 36155516, 2022).
dementia (continued). "CSF neurogranin has been shown to be increased in patients with AD compared to control subjects in several studies and has also been shown to be higher in persons with MCI who progress to AD dementia compared to persons with stable MCI." (PMID 32568193, 2020). "Taken together, elevated levels of neurogranin and YKL-40 could be found in CSF samples of patients with AD compared with those with other dementias and control subjects." (PMID 26698298, 2015). "Large studies showed that neurogranin levels in CSF specifically increased in AD compared to several other neurodegenerative diseases, including PD, FTD, ALS, and vascular dementia, confirming the potential of CSF neurogranin in separating AD dementia from non-AD dementia." (PMID 36831264, 2023). "Therefore, neurogranin and YKL-40 might support the biochemical dementia diagnosis by reflecting aspects of AD pathophysiology complementary to Aβ and tau." (PMID 26698298, 2015). "Samples of patients with AD pathology (AD group) could be separated from those without signs of AD pathology, including other dementias (non-AD group), with an area under the curve (AUC) of 0.85 for neurogranin and 0.66 for YKL-40." (PMID 26698298, 2015). "The co-consideration of neurodegeneration and inflammation markers, neurogranin and YKL-40, improved the accuracy of differential diagnosis of AD from non-AD dementia, achieving an area under the receiver operating characteristic curve of 85%93." (PMID 32284537, 2020). "Neurogranin and BACE1 level differences remained stable over time not only within A/T/N groups but also in patients progressing to more pathological A/T/N stages (e.g. progressing from A+/T−/N− to A + T or N+) and in cases progressing to dementia." (PMID 36262371, 2022).
Parkinson disease (12 papers, 2016 to 2025). A progressive degenerative disorder of the central nervous system characterized by loss of dopamine producing neurons in the substantia nigra and the presence of Lewy bodies in the substantia nigra and locus coeruleus. "Altered CSF levels of NRGN are associated with the impairments in cognition seen in both Alzheimer’s and Parkinson’s disease." (PMID 36386965, 2022). "For instance, patients with Parkinson disease had significantly higher plasma levels of the synaptic vesicle trafficking regulator αSyn compared to healthy controls, and elevated levels of postsynaptic protein NRGN were associated with mild to acute traumatic brain injury." (PMID 39658124, 2024). "In this review, we focus on the role of neurogranin in Alzheimer’s, Parkinson’s, and Crezutzfeldt–Jacob’s diseases." (PMID 39769345, 2024). "In a study conducted a few years ago, the levels of neurogranin in the CSF were compared in people with AD, frontotemporal dementia, Lewy body dementia, Parkinson’s disease, and multiple system atrophy." (PMID 32183332, 2020). "Concentrations SNAP25 and neurogranin were increased in cerebrospinal fluid of Parkinson’s disease patients in a disease specific manner and related to cognitive and motor symptom severity." (PMID 28649607, 2017).
frontotemporal dementia (9 papers, 2018 to 2025). Frontotemporal dementia (FTD) comprises a group of neurodegenerative disorders, characterized by progressive changes in behavior, executive dysfunction and language impairment, as a result of degeneration of the medial prefrontal and frontoinsular cortices. "At the same time, a study examining plasma neuronal-derived exosomes showed that patients with AD and frontotemporal dementia displayed lower levels of plasma neuronal-derived exosomal neurogranin (232 ± 56.5 pg/ml and 1117 ± 227 pg/ml, respectively) compared to the control group (2208 ± 354 pg/ml)." (PMID 35449079, 2022). "It has been found recently that the CSF neurogranin is elevated exclusively in patients with AD but not in other neurodegenerative disorders, such as frontotemporal dementia, LBD, Parkinson's disease, progressive supranuclear palsy, or multiple system atrophy." (PMID 35449079, 2022).
glioma (8 papers, 2018 to 2024). A benign or malignant brain and spinal cord tumor that arises from glial cells (astrocytes, oligodendrocytes, ependymal cells). "Silencing NRGN expression can counteract the inhibition of glioma cell proliferation caused by upregulation of LINC00641." (PMID 38427106, 2024). "NRGN was reported as a tumor suppressor in glioma cells, and we found that it is also associated with good prognosis in EOC." (PMID 34168991, 2021). "Little is known about the role of NRGN in tumors, except that NRGN expression is reduced in gliomas and T-cell lymphomas." (PMID 38427106, 2024). "Studies have revealed that LINC00641 acts as a ceRNA in glioma cells by upregulating NRGN by absorption of miR-4262." (PMID 38427106, 2024). "The low expression of NRGN in GBM plays an antitumor effect in the progression of glioma, which can be used as a new therapeutic target." (PMID 38427106, 2024). "Low levels of LINC00641 expression were observed in glioma cell lines, consistent with our findings, and it intervened in glioma growth by the miR-4262/NRGN pathway." (PMID 38066643, 2023). "LINC00641, as a tumor suppressor, offers new potential therapeutic targets for glioma patients by targeting the miR-4262/NRGN axis in glioma." (PMID 35620284, 2022). "For LINC00641 in glioma, recent research suggested LINC00641 act as an inhibitor of glioma cell proliferation by targeting miR-4262/NRGN axis." (PMID 33750353, 2021). "In conclusion, LINC00641 competitively binds miR-4262 through the ceRNA mechanism to release NRGN, which plays an anti-tumor role in the progression of glioma, providing a new therapeutic target for glioma patients." (PMID 35155216, 2021). "When further exploring the mechanism of LINC00641, it was found that the expression of NRGN was down-regulated in glioma and positively correlated with LINC00641." (PMID 35155216, 2021). "Further experiments demonstrated that LINC00641 enhanced the expression of NRGN in glioma cells through the absorption of miR-4262." (PMID 35155216, 2021). "Immunohistochemical staining showed high expression of DNCH2, ARHGEF6, NPM1, and SRI, while low expression of NRGN and TM4SF2 in gliomas." (PMID 38427106, 2024). "It has been reported that overexpression of LINC00641 in glioma can inhibit cell proliferation and promote cell apoptosis and achieved through LINC00641/Mir-4262/NRGN axis." (PMID 36033510, 2022).
amyloid (7 papers, 2019 to 2025). "This is in contrast to other synaptic proteins measured in CSF, for example, GAP‐43, SNAP‐25, and neurogranin, which are changed only in response to amyloid pathology." (PMID 40522075, 2025). "Probably, NMDA receptors are the common denominator of neurogranin and early amyloidosis in glutamatergic neurons." (PMID 34640593, 2021). "Levels of neurogranin in Aβ 42/40 ratio subgroups do not aid further in the postulation if the patients suffer from AD since neurogranin could be increased regardless of whether amyloid pathology exists or not among AD patients." (PMID 37880775, 2023). "Neurofilament light (NFL), soluble TREM2 (sTREM2) and neurogranin are promising new biomarkers for Alzheimer’s disease (AD), but it is not clear whether they are specific for parenchymal amyloid." (PMID 32176643, 2020).
Brain atrophy (5 papers, 2020 to 2025). Partial or complete wasting (loss) of brain tissue that was once present. "The results showed that GAP43, SNAP25, neurogranin, and synaptotagmin 1 were decreased in neuronal-derived EVs but increased in CSF in patients with AD, and the changes corresponded to the severity of brain atrophy." (PMID 38528511, 2024). "In the present study, we demonstrated that GAP43, neurogranin, SNAP25, and synaptotagmin 1 were significantly changed in both EVs and CSF in patients with AD, and these changes corresponded to the severity of brain atrophy." (PMID 38528511, 2024).
Stroke (5 papers, 2017 to 2025). Sudden impairment of blood flow to a part of the brain due to occlusion or rupture of an artery to the brain. "Other CSF biomarkers such as t-tau, p-tau and neurogranin have also been evaluated in stroke as well as traumatic brain injury to elucidate mechanisms of neuronal injury reflected by particular biomarkers." (PMID 30526557, 2018). "Similar to our findings, CSF t-tau and neurogranin concentrations were related to stroke characteristics." (PMID 30526557, 2018). "To enable a further assessment of neurogranin as biomarker reflecting stroke characteristics, we performed analysis on protein tau as well." (PMID 28854881, 2017). "In our study on AIS, we monitored plasma neurogranin from admission to the hospital until 3 months post-stroke." (PMID 28854881, 2017). "In contrast to tau, of which high levels in both CSF and plasma were related to stroke characteristics like severity and long-term outcome, plasma neurogranin levels were only correlated with infarct volume." (PMID 28854881, 2017). "We analyzed CSF and plasma levels on admission to the hospital, as well as plasma concentrations of neurogranin at different time points after stroke onset." (PMID 28854881, 2017). "A relationship was observed between infarct volume, measured at admission, and concentrations of plasma neurogranin at 24 h (r = 0.510; P < 0.01) and 72 h (r = 0.478; P < 0.01) after stroke onset." (PMID 28854881, 2017). "NRGN is of particular interest in regards to SCD, as a calcium-sensitive, calmodulin-binding,neuron-specific signaling protein, which has been implicated in synaptic development and remodeling, thyroid hormone signaling, stroke and learning." (PMID 33915030, 2021). "Moreover, linagliptin treatment after stroke decreased the presence of peptides derived from neurogranin and from an isoform of the myelin basic protein." (PMID 29776406, 2018). "However, plasma tau has added clinical relevant value compared to neurogranin, since plasma levels of this analyte reflect stroke severity and long-term outcome." (PMID 28854881, 2017). "Blood brain barrier dysfunction has been reported in stroke, which could allow progressive leakage of brain-derived neurogranin into the plasma." (PMID 28854881, 2017). "Also, children with the highest risk of stroke (elevated transcranial Dopper [TCD] velocity) were excluded from the trial, which precludes us from determining a causal relationship between TCD velocities and NRGN or other lead proteins identified." (PMID 33915030, 2021). "Notably, plasma levels of neurogranin 72 h after stroke were weakly inversely related to the CSF/serum ratio of albumin (r = −0.330; P < 0.05) and, at 3 months after stroke onset, to the distance between the infarction and the ventricles (r = −0.688; P < 0.05)." (PMID 28854881, 2017). "Moreover, even though levels in plasma and CSF of neurogranin were significantly associated with infarct volume, levels were not related to stroke severity, neither to long-term outcome, which are clinical relevant characteristics." (PMID 28854881, 2017). "In a clinical context, blood-based mRNA biomarkers, including glial fibrillary acidic protein (GFAP) and neurogranin (NRGN), have shown potential in predicting stroke severity and functional outcomes." (PMID 40896336, 2025). "Hence, more severe stroke may result in higher neurogranin levels." (PMID 28854881, 2017). "Although plasma tau was the best candidate biomarker in the current study, compared to neurogranin, the search continues for non-invasive AIS biomarkers providing an early evaluation of the stroke." (PMID 28854881, 2017). "For each of these time points, the relationship was explored between neurogranin levels and stroke severity (as defined by the National Institutes of Health Stroke Scale (NIHSS)), as well as long-term stroke outcome (represented by the modified Rankin Scale (mRS)) and infarct volume." (PMID 28854881, 2017).
Stroke (continued). "Nonetheless, our current dataset suggests that neurogranin may not have great value as plasma biomarker, or as CSF biomarker, for acute brain injury in case of stroke." (PMID 28854881, 2017). "Yet, neither stroke severity nor long-term outcome were reflected by neurogranin in plasma, or CSF." (PMID 28854881, 2017). "Plasma neurogranin did not correlate with stroke severity, as represented by NIHSS, nor with long-term outcome, i.e. with mRS at 3 months or 12 months after stroke, at any of the time points." (PMID 28854881, 2017).
Lewy body dementia (4 papers, 2019 to 2025). A progressive form of dementia characterized by the presence of protein deposits called Lewy bodies in the midbrain and cerebral cortex, and loss of cholinergic and dopaminergic neurons. "Indeed, most of the data on SNAP-25, β-synuclein, and neurogranin in CSF derive from studies on neurodegenerative disease, such as Alzheimer’s, prion, and Lewy body diseases." (PMID 39708160, 2024).
brain injury (3 papers, 2017 to 2025). Acute and chronic (see also brain INJURIES, CHRONIC) injuries to the brain, including the cerebral hemispheres, CEREBELLUM, and brain STEM. "This study, involving healthy recreational athletes undergoing high-intensity interval training (HIIT), revealed transient increases in neurogranin and other brain injury-associated biomarkers, highlighting exercise as a major confounding variable in biomarker interpretation." (PMID 40981206, 2025). "Neurogranin (NRGN), a synaptic protein essential for plasticity and memory function, is gaining recognition as a promising biomarker for mild traumatic brain injury (mTBI)." (PMID 40981206, 2025). "This systematic review of neurogranin (NRGN) as a biomarker in mild traumatic brain injury (mTBI) reveals a promising but complex picture." (PMID 40981206, 2025). "Yet, in conditions where sudden severe neurological damage occurs, such as in the event of traumatic brain injury (TBI), increased blood neurogranin concentrations have been found." (PMID 28854881, 2017). "Only in conditions of acute severe brain trauma, such as TBI, neurogranin may serve as potential plasma biomarker." (PMID 28854881, 2017).
COVID-19 (3 papers, 2021 to 2025). A disease caused by infection with severe acute respiratory syndrome coronavirus 2. "Protein markers of neuronal dysfunction including amyloid beta, neurofilament light, neurogranin, total tau, and p-T181-tau were all significantly increased in the nEVs of all participants recovering from COVID-19 compared to historic controls." (PMID 33668514, 2021). "Post-COVID-19 neurological symptomatology was associated with higher plasmatic levels of SARS-CoV-2 antibodies and elevated plasmatic biomarkers of neuronal dysfunction (amyloid-beta, light neurofilament, neurogranin, tau, and phosphorylated (p-T181-tau))." (PMID 35625737, 2022).
encephalitis (3 papers, 2022). An acute inflammatory process affecting the brain parenchyma. "Nevertheless, some markers differed in concentration in CSF samples, such as IFNγ and Neurogranin; these were significantly higher in patients with encephalitis." (PMID 35458486, 2022). "Interestingly, we also detected a significant increase in IFNγ and Neurogranin in the CFS of encephalitis patients." (PMID 35458486, 2022). "Anti-LGI1 encephalitis patients have elevated neurofilament light chain protein, glial fibrillary acidic protein and chemokine ligand 13 levels and reduced Visinin-like protein 1, Synaptosomal Associated Protein-25 (SNAP-25) and neurogranin levels in the serumand CSF." (PMID 36685530, 2022).